CD44 (CD44 molecule (IN blood group))
Diseases named in the same sentence as CD44 in open-access papers (continued):
Sharing a sentence is not in itself a finding about the gene and the disease.
breast adenocarcinoma (7 papers, 2017 to 2024). "Cortactin might increase the risk of breast adenocarcinoma metastasis to bone marrow mediated by hyaluronan/cluster of differentiation-44 (CD44) signaling in MCF-7 cell lines indicating that the expression level of CTTN can be positively regulated by CD44." (PMID 33407452, 2021). "The human cervical adenocarcinoma (HeLa) and the mammary adenocarcinoma (MDA-MB-231) cell lines were chosen because they have previously been described as over-expressing CD44." (PMID 34209588, 2021). "Next, we examined both normal and tumor breast tissue samples from four patients with highly aggressive grade 3 breast adenocarcinoma, for the expression levels of CD44 and CD146, by immunohistochemical analysis." (PMID 29121955, 2017). "Moreover, in MCF-7 human breast adenocarcinoma cells, the CD44-1 peptide had the strongest binding affinity for the HLA-A2 molecule, and CD44-1 peptide stimulated DC-CTLs exhibited the most efficient cytotoxic activity against CD44+ MCF-7 cells." (PMID 29298343, 2018). "Second, we observed an inverse relationship between CD44 and CD146 in late stage breast adenocarcinoma tissue samples relative to the adjacent normal tissue, thus supporting our in vitro results." (PMID 29121955, 2017). "Our recent analyses have demonstrated positive downregulation of CD24 and EpCAM expression after oregano administration and decreased expression of CD24 and CD44 after treatment with clove buds in chemically-induced mammary adenocarcinomas in rats." (PMID 30970626, 2019).
crescentic glomerulonephritis (7 papers, 2014 to 2025). A histopathologic term for a pattern of diseases characterized by extensive crescent formation in the glomeruli; patients present clinically with rapid deterioration of renal function, and possible progression to end-stage renal failure within weeks or months. "Genetic deletion of CD44 in mice reduces the number of glomerular lesions in crescentic glomerulonephritis." (PMID 41301516, 2025). "Research has shown that CD44 plays a vital role in the pathogenesis of experimental crescentic glomerulonephritis and collapsing focal segmental glomerulosclerosis." (PMID 37480090, 2023). "Later, another group studied the role of α-SMA as a crescent formation-associated protein in crescentic glomerulonephritis and found that α-SMA, CD44, HA, and osteopontin levels are upregulated at early stages of the disease." (PMID 34009465, 2022). "Research has shown that CD44 plays an important role in the pathogenesis of experimental crescentic glomerulonephritis and collapsing focal segmental glomerulosclerosis." (PMID 35923621, 2022). "These collective data suggest that interactions between α-SMA, CD44, HA, and osteopontin play a role in the development of crescentic glomerulonephritis and that targeting HA-related actions could yield therapeutic benefits." (PMID 34009465, 2022). "Macrophage migration inhibitory factor (MIF), a pleiotropic, proinflammatory cytokine, produced by injured podocytes, is a signaling molecule that mediates pathological PEC proliferation via CD74/CD44, thereby leading to an aggressive and progressive course of crescentic glomerulonephritis." (PMID 35360248, 2022). "CD44 is a marker of activated PEC4,9, and the expression is higher in crescentic glomerulonephritis and in FSGS16,37,38." (PMID 33452384, 2021). "In addition to CD74, the signal transduction of MIF requires the recruitment and activation of CD44, a PEC activation marker, to induce PEC activation and pathological proliferation in crescentic glomerulonephritis." (PMID 35360248, 2022).
diabetic nephropathy (7 papers, 2013 to 2025). "Its receptor, CD44, expressed in multiple tissues, including the kidney, plays a pivotal role in diabetic nephropathy." (PMID 39050866, 2024). "Studies show increased CD44 expression in the glomerulus of rats with diabetic nephropathy, significantly correlating with proteinuria." (PMID 39050866, 2024). "Human and mouse models of focal segmental glomerulosclerosis and diabetic nephropathy have demonstrated CD44-dependent expressions of extracellular matrix protein isoforms in parietal epithelial cells." (PMID 39050866, 2024). "Data obtained in experimental and human FSGS and diabetic nephropathy showed that PECs typically express CD44, thereby producing PEC-derived extracellular matrix protein isoforms in an activated state." (PMID 37108355, 2023). "Glomerular or tubular CD44 overexpression occcurs in humans with IgA-nephropathy, diabetic nephropathy and hypertensive nephrosclerosis as well as in experimental mesangial proliferative glomerulonephritis." (PMID 28002484, 2016). "Lastly, we show the clinical relevance of CD44 and RHAMM in human CKD and diabetic nephropathy, highlighting their implications and therapeutic potential in wider human kidney diseases." (PMID 41301516, 2025). "Functionally, CD44 gene expression was negatively correlated with GFR and positively correlated with serum creatinine concentrations in patients with diabetic nephropathy." (PMID 41301516, 2025). "Finally, analysis of glomerular and tubular fractions of human kidney biopsy samples revealed increased expression of CD44 and RHAMM in chronic kidney disease and diabetic nephropathy, and their expression correlated with markers of kidney dysfunction." (PMID 41301516, 2025). "Using publicly available transcriptomic datasets from the Nephroseq repository, we found that the gene expression of CD44 and RHAMM was increased in kidney biopsies of patients with CKD and diabetic nephropathy in comparison to those from healthy living donors." (PMID 41301516, 2025).
focal segmental glomerulosclerosis (7 papers, 2018 to 2025). A renal disorder characterized by sclerotic lesions in the glomeruli. "CD44 is an activation marker for glomerular parietal epithelial cells (PECs), and CD44-overexpressing glomerular PECs promote glomerular scarring in experimental focal segmental glomerulosclerosis (FSGS)." (PMID 40443664, 2025). "So far, several disease-specific biomarkers have been identified, such as CD44 in membranous nephropathy, dipeptidase 1 (DPEP1) and apolipoproteins in focal glomerulosclerosis (FSGS), and the laminin G-like 3 (LG3) fragments of endorepellin in IgA nephropathy." (PMID 36360378, 2022).
gastritis (7 papers, 2011 to 2025). Inflammation of the stomach. "This is the first report to evaluate CD44 protein expression and polymorphism in Thai gastritis patients." (PMID 29445738, 2017). "Therefore, the association between CD44 rs187116 polymorphism and the expression of CD44 protein in gastritis patients is inconclusive from the present study." (PMID 29445738, 2017). "CHI3L1 was pinpointed as the central driver across the gastritis-to-cancer spectrum, with its upregulation, along with CD44, β-catenin, and c-Myc, noted in gastric precancerous lesions." (PMID 40108688, 2025). "This increased cell proliferation coincided with an increase in the expression of CD44 and Musashi-1 during progression from the normal/gastritis to IM/GC stages." (PMID 21829201, 2011). "Elevated expression of CD44 has been observed in individuals with gastric lesions that have progressed along the gastric precancerous cascade, as well as in those with Helicobacter pylori-positive gastritis." (PMID 40108688, 2025). "CD44 was not detectable in 87% (26 out of 30) of gastritis cases, while was positive in 73% (14 out of 19) of IM and 59% of intestinal type GC (17 out of 27)." (PMID 21829201, 2011).
heart failure (7 papers, 2012 to 2025). Inability of the heart to pump blood at an adequate rate to meet tissue metabolic requirements. "This plays a role in heart failure as the CD44 pathway plays a role in heart failure and it has been found that versican accumulates in patients with ischemic heart failure." (PMID 39194478, 2024). "CD44 is also crucial in the development of cardiac remodelling and myocardial fibrosis, which accelerates the progression to heart failure." (PMID 33230903, 2021). "Transcript levels of several established biomarkers, including Spp1, Sfrp1, Sfrp2, Tnc, Vim, Mmp9, and Tnfrsf1a, and several inflammatory markers that are known to be activated in heart failure, such as Cd44, Cd83, Ccl7, Irf7, and Nr4a2, were upregulated in the Myh6-McmTamDspfl/fl cardiomyocytes." (PMID 40608429, 2025). "In our study cardiac decompensation with clinical heart failure was not present which also may explain the absence of CD44 staining." (PMID 22900226, 2012).
intestinal cancer (7 papers, 2013 to 2024). "Intestinal cancer cell line-based spheroids exhibited heightened levels of CD44+CD133+ cancer stemness, which was improved by chemical-induced RIS." (PMID 39518936, 2024). "We show that deletion of Lef1 in three different Apc-mutant intestinal cancer models accelerates tumor initiation and growth and concomitantly increases the expression of the Wnt-downstream targets Myc and Cd44." (PMID 34788095, 2021). "have shown that CD44 is involved in inhibition of etoposide-induced apoptosis in intestinal cancer cells." (PMID 23468946, 2013). "Intriguingly, OPCs suppressed spheroid derived cancer stem-like cell formation and decreased the expression of intestinal cancer stem cell markers including LGR5, CD44 and CD133." (PMID 29463813, 2018). "Furthermore, OPCs downregulated several well-established large intestinal cancer stem cell markers such as CD133, CD44 and LGR5, indicating that OPCs particularly target cancer stem cells in CRC." (PMID 29463813, 2018).
myeloid leukemia (7 papers, 2012 to 2023). A clonal proliferation of myeloid cells and their precursors in the bone marrow, peripheral blood, and spleen. "Internalization studies were performed in vitro using a chronic human myeloid leukemia cell line (K-562), and showed significant ability of CH/HY NPs to bind CD44 transmembrane receptors expressed on K-562 cell surfaces." (PMID 35631528, 2022). "Based on the growth inhibitory effects of CD44 down-regulation on myeloid leukemia cell lines, we investigated their cell cycle progression of CD44 silencing K562 cells." (PMID 24257075, 2013). "We have presented a literature overview of NDDS design strategies for targeting myeloid leukemia and EGFR/CD44-positive solid tumors." (PMID 33981532, 2021). "Many of those genes inhibited by SID peptide treatment (CD44, TGFβR2, LEF1, TCF7L2, FGF2, FGF5, ID2, PIK3R3) are known as direct TGIF1 targets in myeloid leukemia or embryonic stem cells." (PMID 29179446, 2017). "This article will focus on novel design strategies for nanoscale drug delivery systems, based on the unique molecular signatures of myeloid leukemia and EGFR/CD44-positive solid tumors, and the impact of novel discoveries in molecular tumor profiles on future chemotherapeutic protocols." (PMID 33981532, 2021).
Parkinson disease (7 papers, 2020 to 2025). A progressive degenerative disorder of the central nervous system characterized by loss of dopamine producing neurons in the substantia nigra and the presence of Lewy bodies in the substantia nigra and locus coeruleus. "A recent study has suggested that neuroinflammation in response to neurodegenerative disease such as the toxin 1-methyl-4-phenyl-1,2,3,6-tetrahydropyridine (MPTP) model of Parkinson’s disease is repressed in CD44-deficient mice." (PMID 38877012, 2024). "In addition, CD44 deficiency in a Parkinson’s disease mouse model decreased activation of microglia and astrocytes." (PMID 39095775, 2024). "CD44+ HuAFCs can differentiate into dopaminergic neuron-like cells, which could improve behavioral recovery in a rat model of Parkinson's disease." (PMID 33010000, 2021).
retinal degeneration (7 papers, 2008 to 2025). Degeneration of the retina. "Müller cells upregulate CD44 in response to photoreceptor degeneration in the retinal degeneration slow (rds) mouse." (PMID 39095775, 2024). "Next, we analyzed CD44 expression in retinas from 3 other retinal degeneration mouse models by immunohistochemistry and immunoblot." (PMID 39095775, 2024). "Increased relative expression of the cell surface adhesion receptor CD44 seems to be a very general feature of retinal degeneration considering that it was also present in rd10 mice." (PMID 29354133, 2017). "The amplitude of fold-inductions were similar to those observed for proteoglycans and CD44 in other mouse models of retinal degeneration, namely rd1 (rodless retina), rds (retinal degeneration slow, rd2), and rhodopsin knockout (Rho−/−) mice." (PMID 19050768, 2008). "In the present work, we showed that NGC, IMPG2, and CD44 mRNA expression was induced during retinal degeneration in Rpe65−/− mice." (PMID 19050768, 2008). "CD44 was highly expressed in all 3 other retinal degeneration mouse models, suggesting that photoreceptor degeneration, independent of the genetic cause, leads to upregulation of CD44 expression in Müller cells." (PMID 39095775, 2024). "In addition, CD44, a Muller glia expressed gene that is increased upon retinal degeneration, is upregulated in OC2-KO retina microarrays." (PMID 25313862, 2014). "An increased mRNA expression of the genes coding for the extracellular matrix proteins neuroglycan C (NGC), interphotoreceptor matrix proteoglycan 2 (IMPG2), and CD44 antigen (CD44) has been observed during retinal degeneration in mice with a targeted disruption of the Rpe65 gene (Rpe65−/− mouse)." (PMID 19050768, 2008). "For example, in the retinal degeneration slow (rds) mouse and in the Royal College of Surgeons (RCS) rat model, CD44 was increased in Müller cells." (PMID 39095775, 2024). "At 8 months of age, Cx3cr1 mice did not present manifestations of retinal degeneration, yet we observed a strong upregulation of central memory T cells (CD44+CD62L+) within their ocular immunophenotype compared to C57Bl/6J controls." (PMID 39975545, 2025).
rhabdomyosarcoma (7 papers, 1999 to 2023). A rare aggressive malignant mesenchymal neoplasm arising from skeletal muscle. "The aim of this study was to evaluate the role of the standard isoform of CD44 in predicting the clinical behaviour of rhabdomyosarcoma." (PMID 10360676, 1999). "Additionally, PAX5, LTB and CD44 (markers of stem cells) were significantly colocalized in the scRNA-seq data of the human alveolar rhabdomyosarcoma cell line Rh41." (PMID 33397394, 2021). "This study aimed to evaluate the expression of the selected stem cell markers CD24, CD44, CD133, and ALDH1A1 in rhabdomyosarcoma in children and to determine their prognostic significance in this disease." (PMID 36010245, 2022).
skin cancer (7 papers, 2014 to 2023). "The expression levels of CD44 and CD133 were decreased by knockdown of ITGAV and TIMP-1 in skin cancer cells compared to control cells." (PMID 30486830, 2018). "In accordance with reduced stemness, the expression of CSC markers, CD44 and CD133, were decreased in IL-32γ overexpressing skin cancer cells." (PMID 30486830, 2018). "Therefore, we examined whether VEGF-C affects cancer stemness in skin cancer cells and found that knockdown of VEGF-C significantly decreased the expression of the CSC markers SOX2, OCT4, KLF4, NANOG, CD133, CD34 and CD44 as well as ALDH activity, which is a hallmark of CSCs." (PMID 27901498, 2017). "An Oncomine database analysis also demonstrated that VEGF-C expression was positively correlated with the expression of some CSC markers, such as OCT4, KLF4, NANOG, CD44, CD34 and CD133, suggesting that VEGF-C increases the CSC features of skin cancer cells." (PMID 27901498, 2017). "Consistently, the expression of Slug was positively correlated with the expression of CSC markers such as CD44, NANOG, ALDH1A1 and KLF4 in skin cancer." (PMID 27901498, 2017). "Recently, a comparative expression analysis of CD44 and ALDH1A1 putative cancer stem cell markers in various skin cancer subtypes was performed." (PMID 27505250, 2016). "The new knowledge obtained from our HA/CD44-signaling strategies and HA-based/vitamin D therapeutic approaches should reveal new avenues for possible treatment of UVR-induced skin cancers." (PMID 26029210, 2015). "However, responsiveness to Onco-P20 is also an intrinsic characteristic of different cell lines related to the CD44 level of expression that is not necessarily over-expressed in skin carcinomas compared to normal cells." (PMID 34073987, 2021).
T-cell acute lymphoblastic leukemia (7 papers, 2017 to 2025). Acute lymphoblastic leukemia of T-cell origin. "In acute T-cell lymphoblastic leukemia, high levels of CD44 on cells were noted, and a positive correlation was observed with the development of infiltration of the internal organs of patients." (PMID 39851489, 2025). "A correlation between CD44 expression and chemoresistance was also reported in T-cell acute lymphoblastic leukemia." (PMID 34298843, 2021). "In case of T-cell acute lymphoblastic leukaemia, CD44 promoted chemoresistance by supporting enhanced drug efflux." (PMID 29371972, 2017). "In a previous study performed on T-cell acute lymphoblastic leukemia (TALL) mice, it has been shown that CD44 knock-down augmented chemosensitivity to doxorubicin and dexamethasone, suggesting that CD44 is involved in drug resistance in TALL." (PMID 35432798, 2021).
bladder transitional cell carcinoma (6 papers, 2017 to 2025). The most common morphologic subtype of urinary bladder carcinoma (over 90% of cases). "In our preliminary data, we tried to isolate CSCs form human bladder transitional cell carcinoma with CD44 + and CD133 + magnetic-activated cell separation purification system." (PMID 38462600, 2024). "Subsequently, by using serial xenograft models, they identified a subpopulation of tumor cells with expression of CD44 from freshly isolated human bladder transitional cell carcinoma." (PMID 35903544, 2022). "The investigators found that approximately 40% of the bladder transitional cell carcinomas contained CD44+ cells." (PMID 35903544, 2022). "Later, the authors investigated heterogeneity of different CD44+ bladder transitional cell carcinoma subpopulations and they detected a variety of self-renewal proteins in active form, such as nuclear Bmi-1, Stat3, and p-catenin." (PMID 35903544, 2022). "Analysis of the heterogeneity of different CD44+ subsets in bladder transitional cell carcinoma demonstrated many proteins that are involved in self-renewal such as nuclear Bmi-1, Stat3, and β-Catenin." (PMID 29029546, 2017). "The concept that a loss of CD44 expression, rather than its overexpression, could signify a more aggressive phenotype is supported by evidence from a large study of 410 primary urothelial bladder cancers, which found that absent CD44v6 expression was an independent predictor of poor outcome." (PMID 41514534, 2025).
Cerebral ischemia (6 papers, 2015 to 2024). Restriction of arterial blood supply to the brain associated with insufficient oxygenation to support the metabolic requirements of the tissue. "Some evidence suggests that CD44 is involved in exacerbating cerebral ischemia possibly through the production of the pro-inflammatory cytokine IL-1β, with CD44-deficient mice significantly protected from cerebral ischemia and reduced levels of IL-1β." (PMID 29519253, 2018). "A recent study has revealed the role of CD44 in the SRGN-mediated activation of microglia during MCAO model of focal brain ischemia in mice." (PMID 38877012, 2024). "A few studies mentioned that CD44 was induced under brain ischemia." (PMID 38287411, 2024). "Interestingly, in this study, we found that CD44 was mainly expressed by microglia and less expressed by other neural cells (like astrocytes) at 1 day after brain ischemia." (PMID 38287411, 2024).